MIR6072 (microRNA 6072)
Synonyms: hsa-mir-6072
Gene: MicroRNA gene on chromosome 10 (2,076,019 to 2,076,089, reverse strand). Ensembl gene ENSG00000278069.
Homologues: Orthologues: chimpanzee MIR6072 (100% identical).